NFE2L2 (NFE2 like bZIP transcription factor 2)
Diseases named in the same sentence as NFE2L2 in open-access papers (continued):
Sharing a sentence is not in itself a finding about the gene and the disease.
cancer (continued). "TMB has been shown to be a predictive biomarker for ICIs in various cancers, implying that cancer patients with NFE2L2 MUs may benefit from ICIs." (PMID 37794491, 2023). "Only NFE2L2, CDKN2A, and FBXW7 were rarely mutated in normal samples than cancer samples." (PMID 36991467, 2023). "We also performed meta-analysis for each cancer type to summarize results from different cohorts, and found that NFE2L2 MU did not have a significant association with OS (HR: 0.94, 95% CI 0.70 − 1.26)." (PMID 37794491, 2023). "Second, the low frequency of NFE2L2 MUs (1.9–3.6% in pan-cancers) might restrict the therapeutic use of detecting NFE2L2 MUs and explaining the mechanism of disease progression in NFE2L2 mutated tumors." (PMID 37794491, 2023). "In cancer, specific methylation and other alterations of the NFE2L2 promoter have been documented, which can alter the expression levels of NRF2, linked to carcinogenesis through metabolic reprogramming, tumor promotion, inflammation, and resistance to therapy." (PMID 36978889, 2023). "Co-mutation of KRAS and KEAP1/NFE2L2 predicts worse survival to chemotherapy and immunotherapy, and Nrf-2-regulated ROS homeostasis has been linked to chemotherapy resistance in NSCLC and other cancers." (PMID 36591457, 2022). "The largest APOBEC-related cancer effects are attributable to mutations in PIK3CA and NFE2L2." (PMID 35872531, 2022). "NFE2L2 is a mediator of the transcription of genes encoding detoxifying enzymes, and antioxidant and multidrug resistance proteins and activation of NFEL2L can cause chemotherapy and radiation resistance in cancer cells." (PMID 36624801, 2022). "SOX2, UBTF, NFE2L2, TCF3 and STAT3 were underlined as common transcriptional factors, which are responsible for the upregulation of genes involved in processes of the epithelial–mesenchymal transition, cancer stemness, invasion and migration of GBM." (PMID 36231068, 2022). "Interestingly, a case report of HCC in a 17-month-old patient with biallelic germline ABCB11 mutations found somatic mutations in the cancer-related genes beta-catenin (CTNNB1) and nuclear factor erythroid 2-related factor 2 (NFE2L2)." (PMID 36010647, 2022). "The CRSO findings support that NFE2L2‐mediated NRF2 activation may be an essential driver in multiple cancers types." (PMID 33769711, 2021). "Notably, mutations in KEAP1/NFE2L2 and those in EGFR exclude each other in all cancer types with high somatic mutation rates in these genes, speaking for a high functional overlap of both pathways." (PMID 33916908, 2021). "Surprisingly, this mechanism only was seen in NFE2L2-overexpressed NSCLC, raising the idea that the genes induced by NRF2 in cancer cells might be different from those induced in NFE2L2-WT background." (PMID 34440648, 2021). "Surprisingly, expression of DNAJA3 and NFE2L2 mRNA was positively correlated in both normal and cancer tissues in cohort GSE15420, and the correlation coefficient R reached 0.48 with a p value of 1.7 × 10−13 in normal tissues, and in cancer tissues, the R reached to 0.22 with a p value of 0.0015." (PMID 33406664, 2021). "Many studies revealed that the NFE2L2 pathway was a “double‐edged sword” in cancer." (PMID 34617407, 2021). "Given the key role of NFE2L2 in ferroptosis, it may be a promising target for drug development for treating malignant tumors." (PMID 34938739, 2021). "However, when NFE2L2 is overexpressed in cancer cells, it promotes their drug and radiotherapy resistance." (PMID 34446793, 2021). "Indeed, it is known that also the NFE2L2 promoter is subjected to epigenetic modifications in some kinds of cancer." (PMID 33233657, 2020).
cancer (continued). "The present study revealed that NFE2L2 was abnormally expressed and significantly correlated with mismatch repair (MMR) gene mutation levels and DNA methyltransferase expression in human pan-cancer." (PMID 33101586, 2020). "Moreover, the correlation between NFE2L2 expression and immune checkpoint markers implies the role of NFE2L2 in regulating tumor immunology in cancers, especially in LGG." (PMID 33101586, 2020). "All NFE2L2 levels in cancer tissues were down-regulated in relation to normal tissue." (PMID 32824922, 2020). "Interestingly, the mutational frequency in NFE2L2 and KEAP1, 3% and 5% respectively, is much lower than in some other cancer types." (PMID 33276631, 2020). "These previous findings indicate NFE2L2 may be abnormally expressed in various cancers and play important roles in cancer progression and patients' prognosis." (PMID 33101586, 2020). "Examination of second-generation sequencing of a large number of tumours deposited in the catalogue of somatic mutations in cancer (COSMIC) and the cancer genome atlas (TCGA) databases revealed that NFE2L2 and KEAP1 are mutated in various common cancers, including lung, head and neck, and bladder." (PMID 33276631, 2020). "Therefore, the correlation between NFE2L2 expression and immune infiltration in human pan-cancer was further studied." (PMID 33101586, 2020). "Notably, NFE2L2 expression was significantly correlated with patients' OS in 7 types of cancer (ACC, KIRC, LGG, MESO, PAAD, SARC, and UCS)." (PMID 33101586, 2020). "In addition, several studies have indicated that NFE2L2 is upregulated in different types of cancers and correlates with tumor progression, aggressiveness, and poor prognosis." (PMID 33101586, 2020). "Results revealed that NFE2L2 was abnormally expressed in 22 of these cancers." (PMID 33101586, 2020). "Taken together, these results reveal that NFE2L2 is abnormally expressed in different cancers." (PMID 33101586, 2020). "This is one demonstration of the detrimental side of NFE2L2, as a promoter of cancer metastasis." (PMID 31752195, 2019). "Molecular testing in cell lines exhibited that the ESR1 gene was lower expressed in all four EOC cell lines, which could be upregulated by NFE2L2 silencing in the subsequently NFE2L2-downregulated cancer cell lines." (PMID 30597961, 2018). "This minireview describes the recent updates about the deregulation mechanisms of the KEAP1/NRF2 pathway, with a particular focus on the epigenetic modulation of KEAP1 and NFE2L2 and their cellular significance and potential impact on cancer patient management." (PMID 29643973, 2018). "Activating mutations in Nrf2, inactivating mutations in KEAP1, and epigenetic dysregulation of KEAP1 and NFE2L2 have been observed in various types of cancers, and these changes are more common in cells and tissues that demonstrate de novo or acquired resistance to various types of chemotherapy." (PMID 28383481, 2017). "For instance, modeling of the NFE2L2 pathway suggests that the high NFE2L2 expression that typically occurs in cancer cells promotes chemoresistance and suggests apparently opposite roles in antioxidant and ROS-mediated cancer signaling." (PMID 28744456, 2017). "Taken together, it seems that NFE2L2 plays a dual role in cancer." (PMID 27770790, 2016). "In addition to cancer prognosis, now well validated in the current study, NFE2L2 holds promise for the management of multiple cancers." (PMID 26596768, 2015). "Further, we streamlined our study to five data sets, which were representative of the most distinct inflammation/injury and cancer signatures of interest and constructed a canonical first-generation regulatory network for Nrf2 (Nfe2l2) and Nfkb1, representing 59 nodes and 253 potential interactions." (PMID 19050705, 2008).
cancer (continued). "Interestingly, by using Gepia2 web server we compared the expression levels of CASP8 and NFE2L2 genes in tumors and normal tissues from The Cancer Genome Atlas (TCGA) database; the expression of both genes is aberrantly upregulated in several cancers, including GBM." (PMID 41053176, 2025). "Conversely, persistent or constitutive activation—often due to mutations in KEAP1 or Nuclear factor erythroid 2-like 2 (NFE2L2) which encodes NRF2, or metabolic rewiring—confers a tumor-promoting phenotype, enhancing survival, proliferation, and treatment resistance in established cancers." (PMID 41470226, 2025). "While its activation is initially protective, the persistent or dysregulated activity of NFE2L2 has been shown to facilitate tumor growth by enhancing cellular survival under stress conditions and promoting cellular metabolism changes that support cancer progression." (PMID 41154628, 2025). "The well-established NFE2L2/KEAP1 system has emerged as the cellular stress-sensitive master transcriptional regulator of various downstream targets, predominantly genes encoding anti-oxidative and detoxification pathways, associated with both cancer and cardiovascular susceptibility in humans." (PMID 37627583, 2023). "The finding that tumorigenesis can be driven by any two arms of the β-catenin/Hippo/NFE2L2 axis has permitted the identification of a small subset of coordinately regulated tumor-specific transcripts, some of whose levels correlate with inferior long-term outcomes in HB and other cancers." (PMID 33919162, 2021). "However, the roles of NFE2L2 in human cancers are still unclear." (PMID 33101586, 2020). "On the other hand, the telomere length-associated gene TERC and oxidative stress response gene NFE2L2 were more frequently amplified in the CHRNB4-high subgroup, which could immortalize cells and against oxidative stress for promoting cancer cell survival and escaping apoptosis." (PMID 32455963, 2020). "As NFE2L2 becomes dysregulated, cells may acquire several traits, including proliferation, apoptosis resistance, and a profound resistance to drugs and radiotherapy, which may promote tumor growth and cancer pathogenesis." (PMID 26596768, 2015). "We hypothesized that NFE2L2-mediated gene expression would reflect cancer severity and progression." (PMID 26596768, 2015). "The Nuclear Factor Erythroid 2-Related Factor 2 (Nrf2), coded by NFE2L2 gene, has emerged as a key player in chemoresistance and tumoral progression across multiple cancer types, including BC." (PMID 42196483, 2026). "To mitigate this, we focused on assessing mRNA levels of key antioxidant enzymes (NFE2L2, HMOX1, SOD2, CAT) in both thyroid normal and cancer cells to gain insight into their oxidative stress response ability." (PMID 40927570, 2025). "Some groups have shown the effects of phytocompounds, such as sulforaphane and luteolin, on the methylation status of NFE2L2/KEAP-1 promoters, thereby influencing cell survival and tumor progression in different cancer entities." (PMID 38666930, 2024). "Loss of KEAP1, a negative regulator of the antioxidant response transcription factor NFE2L2/NRF2, activates the PPP in KRAS-mutant LUAD cancers." (PMID 38841622, 2024). "These cofactors enhance the transcriptional activity of NFE2L2, thereby amplifying the expression of SLC7A11 and contributing to the inhibition of ferroptosis in cancer cells." (PMID 39534872, 2024). "NFE2-like basic leucine zipper transcription factor 2 (NFE2L2, also known as NRF2), is a key transcription factor in the cellular defense against oxidative stress, playing a crucial role in cancer cell survival and resistance to therapies." (PMID 39534872, 2024).
cancer (continued). "Therapeutically, targeting NFE2L2-dependent expression of ALDH1A1 and ALDH1A3 offers a promising strategy to enhance the sensitivity of cancer cells to chemotherapy." (PMID 39534872, 2024). "STK11 is a tumor suppressor involved in cell motility and metabolism and NFE2L2 plays a key role in oxidative stress response, while PTP4A1 has been recently identified as a novel therapeutic target in cancer." (PMID 38191367, 2024). "The situation in 133 pan-cancer patients is similar; ICI improves OS in patients with NFE2L2 MU compared with other treatments." (PMID 37794491, 2023). "To further support these conclusions, we analyzed the cancer cell line database across all members of the NFE2:MAF family including MAFG, MAFF, MAFK, NFE2L1, and NFE2L2." (PMID 37985752, 2023). "Cancer cells escape oxidative damage by upregulating NRF2 (NFE2L2), a transcriptional activator that induces several genes including its own (Nfe2l2)." (PMID 36765862, 2023). "The NFE2L2 (NRF2) oncogene and transcription factor drives a gene expression program that promotes cancer progression, metabolic reprogramming, immune evasion, and chemoradiation resistance." (PMID 37716475, 2023). "As a homolog of NFE2L2, NFE2L3 has been proven to be related to multiple phenotypes of malignant tumors as well, including proliferation and epithelial-mesenchymal transition (EMT)." (PMID 35664314, 2022). "In our study, we analyzed 14 genes that are significantly related to some or most anticancer drugs, such as FANCD2, HSPA5, NFE2L2, ACSL4, and DPP4 in the Cancer Therapeutic Response Portal Database." (PMID 35309947, 2022). "Nuclear factor erythroid 2-related factor 2 (Nrf2, also called NFE2L2) plays an important role in cancer chemoresistance." (PMID 33414469, 2021). "In our study, we also found that NFE2L2 expression was closely correlated with that of 4 DNA methyltransferases (DNMT1, DNMT2, DNMT3A, and DNMT3B) in human cancers, especially in COAD, KIRP, LGG, and UVM." (PMID 33101586, 2020). "Evidently, NFE2L2 expression is closely related to the expression of DNMT1, DNMT2, DNMT3A, and DNMT3B across human cancers, especially in COAD, KIRP, LGG, and UVM." (PMID 33101586, 2020). "First, we downloaded the scores of 6 types of infiltrating immune cells in 33 types of cancer from the TIMER database and then analyzed the correlation between the NFE2L2 expression level and immune infiltration levels." (PMID 33101586, 2020). "SOX2 can enhance translation of oncogenic proteins driven by key cancer transcription factors, including NFE2L2, while signaling from PIK3CA can maintain NFE2L2 protein levels." (PMID 31395880, 2019). "Following effective silencing of NFE2L2 with siRNA to evaluate the impact on ESR1 expression, an elevated expression of ESR1 in the NFE2L2 downregulated cancer cell lines OVCAR3 (p = 0.003) and ES2 was noted (p < 0.001)." (PMID 30597961, 2018). "DHA was thus shown to induce nuclear translocation of the oxidative stress sensor NFE2L2 and thereby to trigger an antioxidative response in RPE cells and cancer cells." (PMID 29694386, 2018). "The therapeutic strategy to reduce GSH levels in cancer is hampered by the fact that GSH depletion leads to up-regulation of antioxidant genes, as shown by the transcription activator NFE2L2 in response to oxidative stress." (PMID 29285300, 2017). "The Nrf2 protein gene, NFE2L2, expression was not significantly changed in gastric cancer tissues (n = 408) compared with normal gastric tissues (n = 211) only a few cancer tissues exhibited differential expression." (PMID 40264514, 2025). "Cancer cell lines harboring mutations in KEAP1, a negative regulator of NFE2L2, are typically more resistant to small molecule inducers of ferroptosis than KEAP1 wild-type cell lines." (PMID 39025451, 2024). "In cancer cells, the overexpression of G6PD and the subsequent activation of the pentose phosphate pathway are often driven by oncogenic signaling pathways, including the NFE2L2 pathway." (PMID 39534872, 2024).
cancer (continued). "NFE2L2 and STAT3 are key pro-survival molecules, and thus, their targeting may represent a promising anti-cancer strategy." (PMID 37511362, 2023). "From the cancer-related protein dataset of DisProt database, we found a conditional essential IDP with 100% disorder content, called ‘nuclear factor erythroid 2-related factor 2’ (NFE2L2, Uniprot ID: Q16236)." (PMID 36458923, 2023). "The cancer target PDB ID 1RY0 (AKR1C3) showed the highest interactions with the majority of the NCs, followed by 1HFQ (DHFR), 3ZGC (NFE2L2), 4AF3 (AURKB), 4K33 (FGFR3), 5P21 (HRAS), 2I0V (CSF1R), and 3ZIM (PIK3CA) protein targets and least interaction was found with the 1M9Z (TGFBR2) protein." (PMID 36387366, 2022). "Compared to Del-c1 and c3, the majority of cancer genes were deleted by DEL-c2, such as CDKN2A (207/528), FHIT (133/528), KDM6A (42/528), RB1 (27/528), FAT1 (23/528), NFE2L2 (13/528), ERBB4 (20/528), CUL3 (11/528), PTEN (9/528), ZNF750 (13/528) and NOTCH1 (8/528)." (PMID 36272974, 2022). "Binding motifs for many essential TFs, such as RXRA, NFE2L2, ESRRA, IRF2, RELA, ESRRA, SOX2, and SMAD2/3, key TFs that mediate TGFβ signaling in epithelial-mesenchymal transition (EMT) and cancer metastasis, were enriched in common gained or LNC-specific gained enhancers, with some overlapping TFs." (PMID 34294701, 2021). "Transcription factor NFE2L2 (nuclear factor, erythroid 2 like 2), also named NRF2, functions as an oncogene or tumor suppressor, it regulates the cellular antioxidant response and promotes cancer chemotherapy resistance, metastasis, and progression 26-28." (PMID 32489453, 2020). "Since non-tumor-related factors may cause death during follow-up, we then analyzed the relationship between NFE2L2 expression and DSS in 33 cancers." (PMID 33101586, 2020). "KEAP1 was not considered in our initial screen due to absence in the Cancer Gene Census38, providing an opportunity to further test NFE2L2 responsiveness." (PMID 28959951, 2016). "The disruption of this partnership involving the ubiquitination of NFE2L2 through the KEAP1/CUL3/RBX1 complex and its posterior proteasomal degradation, which leads to the constitutive activation of antioxidant response genes is known in several cancer types." (PMID 26792175, 2016). "Activating alterations in NFE2L2, coding for the stress response transcription factor NRF2, have not yet been shown to cause cancer in mice, partially because mice with activated NRF2 signaling in the germline die at young ages due to esophageal hyperkeratosis." (PMID 41279109, 2025). "Thus, SLC7A11 and GCLC expression could be defined as a cancer signature of GAS41 amplification in NSCLC (KEAP1 and NFE2L2 WT)." (PMID 38514704, 2024). "Since survival analysis by cancer type revealed that NSCLC patients with NFE2L2 MU had a poorer OS, but not NFE2L2 mutated NSCLC patients treated with ICIs, we used TCGA NSCLC transcriptomic data to assess signal pathway alterations between NFE2L2 MU and NFE2L2 WT groups." (PMID 37794491, 2023). "To kill cancer cells, SDT shifts the intracellular environment toward pro-oxidant conditions, due to reactive oxygen species (ROS) accumulation; we, thus, investigated the mRNA expression of oxidative stress-related genes, namely, NFE2L2 and NQO1 in tumor tissue at 72 h after SDT (day 11)." (PMID 34681196, 2021). "In conclusion, the results of the present study indicated that NFE2L2 overexpression correlates with poor prognosis of patients and increases the infiltration levels of B cells, CD8+ T cells, CD4+ T cells, macrophages, neutrophils, and dendritic cells in many cancers, especially in LGG." (PMID 33101586, 2020).